SAA1 (serum amyloid A1)
Diseases named in the same sentence as SAA1 in open-access papers (continued):
Sharing a sentence is not in itself a finding about the gene and the disease.
Sepsis (continued). "SAA-1, a classical acute-phase reactant, was selected because in our proteomic data it showed upregulation in sepsis compared with both healthy donors and HLH, while remaining largely unchanged between HLH and healthy donors, suggesting its value as a differential marker for both diseases." (PMID 41463121, 2025). "Our findings suggest that inhibition of NF‐κB during sepsis may increase survival and attenuate SAA1‐induced muscle atrophy." (PMID 31441598, 2020). "The processing of SAA1 included the cleavage of the terminal peptide D/PNHFRPAGLPEKY from the most hydrophilic point of SAA1 on the COOH side of the cystatin C binding that was most apparent in ICU-Sepsis patients compared to all other diseases and controls." (PMID 32636717, 2020). "SAA1 has been implicated in many different diseases including sepsis and the intact full length protein is unlikely to serve as a specific biomarker." (PMID 32636717, 2020). "The processing of SAA1 including the cleavage of the C-terminal tryptic peptide DPNHFRPAGLPEKY from the most hydrophilic point of SAA1 on the COOH side of the Cystatin C binding was most apparent in ICU-Sepsis patients compared to all other diseases and controls." (PMID 32636717, 2020). "Thus, the processing of SAA1 in ICU-Sepsis patients apparently varied compared to all other diseases and controls." (PMID 32636717, 2020). "Inflammation-induced muscular SAA1 accumulation was reproduced in a sepsis mouse model." (PMID 24651840, 2014). "In addition, SAA1 knockdown in TECs decreased NETs formation in the lung and alleviated lung injury induced by LPS, indicating that, during sepsis, SAA1 released by TECs can mediate remote organ injury." (PMID 40936924, 2025). "Whether SAA1 affects the proteasome function in muscle during sepsis is unknown." (PMID 34572540, 2021). "The processing of SAA1 may play an unappreciated role in the inflammatory response to Sepsis." (PMID 32636717, 2020). "Thus there was disease associated variation in the processing of SAA1 in ICU-Sepsis versus ICU controls or other diseases and normal." (PMID 32636717, 2020). "Its two human isoforms, SAA1 and SAA2, are predominantly produced by hepatocytes and contribute to systemic immune responses in sepsis but also in a range of other inflammatory conditions, such as arthritis." (PMID 40595432, 2025). "For ELISA validation, six proteins were selected (SAA-1, LRG1, PSMB1, sCD300a, sCD300b, and sCD25) in a larger cohort (21 healthy donors, 37 sepsis/septic shock patients and 15 HLH patients)." (PMID 41463121, 2025). "Acute phase reactants, including c-reactive protein (CRP), serum amyloid A-1 (SAA1), and serum amyloid A-2 (SAA2), significantly discriminated sepsis patients from healthy controls." (PMID 40864331, 2025). "Sepsis groups showed significantly elevated levels of acute-phase reactants, including CRP, SAA1, and SAA2, reflecting the immediate immune response to infection of the host." (PMID 40864331, 2025). "Interestingly, modulating EVs release from TECs or SAA1 expression in TECs also alleviated remote lung injury induced by LPS, indicated that TECs-derived EVs may participate in kidney‒lung crosstalk during sepsis." (PMID 40936924, 2025). "In sepsis-induced lung injury, BMSC-EXO serum amyloid A1 (SAA1) reduces inflammation and endotoxin levels, promoting alveolar macrophage function and attenuating lung damage." (PMID 41488672, 2025). "In sepsis, inflammatory cytokines, such as interleukin‐6 (IL‐6), IL‐1β, tumour necrosis factor (TNF), and the acute phase protein, serum amyloid A1 (SAA1), are increased in serum and skeletal muscle of patients and mice." (PMID 37209006, 2023). "In addition, we identified in experimental sepsis another sepsis-suppressed gene linked to muscle dystrophy, anoctamin 5 (Ano5), and discovered its potentially beneficial regulation by the NTCI, Importantly, the treatment with the NTCI lowered the expression of Saa1 in the lungs by 2.7-fold." (PMID 37638006, 2023).
Sepsis (continued). "Compared with sepsis, the three proteins with the largest decrease in HLH were protein sidekick-1 (SDK1), serum amyloid A-1 protein (SAA1), and C-reactive protein (CRP )." (PMID 37653176, 2023). "SAA1;SAA2, CRP, ITIH3, SERPINA1 are acute phase proteins that are also dysregulated in other inflammatory states including sepsis." (PMID 36812516, 2022). "Our data are in line with the literature, describing the participation of SAA1 in the inflammatory response of TLR2/4 activation in periodontitis, myotube atrophy, or sepsis, among others." (PMID 34070533, 2021). "They showed that SAA1 via the TLR2/TLR4/NF-κB signaling pathway mediates C2C12 myotube atrophy in vitro and sepsis-induced muscle atrophy in mice in vivo." (PMID 34572540, 2021). "The cleavage of the terminal peptide D/PNHFRPAGLPEKY from the most hydrophilic point of SAA1 on the COOH side of the cystatin binding site was most frequently observed in ICU-Sepsis compared to all other treatments." (PMID 32636717, 2020). "The application of 2D electrophoresis of blood fluid together with mass spectral analysis detected increased levels of serum amyloid (SAA1), inter alpha trypsin inhibitor (ITIH3) and APOJ in sepsis." (PMID 32636717, 2020). "Cleavage of the SAA1 protein to release peptides from the COOH terminal and elsewhere was more frequent in sepsis compared to all other diseases and controls." (PMID 32636717, 2020). "Peptides and/or phosphopeptides of common plasma proteins such as ITIH3, SAA2, SAA1, and FN1 showed increased observation frequency by Chi square (χ2 > 9, p < 0.003) and/or precursor intensity in sepsis." (PMID 32636717, 2020). "In agreement with the literature, peptides from ITIH3, SAA2, SAA1, and FN1 showed variation in observation frequency between ICU-Sepsis versus ICU Control." (PMID 32636717, 2020). "The SAA1 tryptic peptide D/PNHFRPAGLPEKY, was cleaved from the COOH terminus of SAA1 and was specific to ICU and ICU-Sepsis patients similar to that observed in patients with the auto inflammatory disorder Kawasaki’s disease." (PMID 32636717, 2020). "Of note, serum SAA1, HAMP1, and MMP9 levels are elevated during human sepsis and have been investigated as prognostic biomarkers (66, –, 68)." (PMID 27303721, 2016). "Conclusions: sCD300a, sCD300b and sCD25 could be specific serum biomarkers for HLH diagnosis, and SAA-1 and LRG1 might be useful biomarkers for differential diagnosis between sepsis and HLH." (PMID 41463121, 2025). "Differential analysis identified 6 proteins that were significantly upregulated in sepsis serum samples, including MMP9, lipocalin-2 (LCN2), serum amyloid A1 (SAA1), serum amyloid A2 (SAA2), paired-like homeobox 2B (PHOX2B), and lactoferrin (LTF) (|log2FC| > 1, P < 0.05)." (PMID 41306770, 2025). "Thus, SAA-1 and LRG1 showed very good discrimination between HLH and sepsis, whereas PSMB1 displayed excellent discriminatory performance in this dataset." (PMID 41463121, 2025). "In line with the expression patterns, ROC curve analyses for the differential diagnosis between HLH and sepsis yielded excellent AUC values for PSMB1 (0.98) and very good values for SAA-1 and LRG1 (>0.8), indicating superb discriminatory performance in our cohort." (PMID 41463121, 2025). "According to our results, the serum concentration of SAA-1 and LRG1 could contribute to the differential diagnosis between HLH and sepsis." (PMID 41463121, 2025). "More intriguingly, exogenous SAA1 exacerbated noncanonical inflammasome-mediated sepsis, pathogenesis, and lethality." (PMID 38297162, 2024). "In a previous proteomics study conducted by our group in adult sepsis patients, we proposed a set of 10 proteins (AT-III, CLUS, SAA-1, HO-1, IL-6, IL-18, sCD25, sCD163, sICAM-1 and sFas) that can be considered as a complementary tool for the clinicians in the diagnosis of sepsis." (PMID 35329889, 2022).
Sepsis (continued). "SAA-1, sCD25 and LRG1 were able to separate septic from healthy donor, so they could be used together with other clinical and analytical features to improve sepsis diagnosis in children." (PMID 35329889, 2022). "Thus, by monitoring the processing of SAA1 in EDTA plasma by LC–ESI–MS/MS it might be possible to detect and resolve ICU-Sepsis patients from the background population of ICU." (PMID 32636717, 2020). "Furthermore, SAA1 cleavages on the NH2 terminal side of the Cystatin binding site were observed in ICU-Sepsis but not ICU Control." (PMID 32636717, 2020). "All septic patients were positive for at least one of these three proteins (SAA-1, sCD25 and LRG1) and all healthy donors were negative, which allowed us to split up all the patients and control by analysis these three proteins, remarking the value of proteins in the diagnosis of sepsis." (PMID 35329889, 2022).
amyloidosis (29 papers, 2010 to 2025). A disorder characterized by the localized or diffuse accumulation of amyloid protein in various anatomic sites. "In correlation analysis between immune score and DEGs, SAA1 (Serum Amyloid A), a protein associated with Amyloidosis, was found most positively correlated with immune score (Spearman r = 0.36, P < 0.0001)." (PMID 38627760, 2024). "According to GeneCards, diseases associated with the Saa1 gene include serum amyloid A1 amyloidosis and amyloidosis." (PMID 39062058, 2024). "The -13C/T polymorphism, in the 5′-flanking region of the SAA1 gene is associated with the SAA1.3 allele and susceptibility to amyloidosis in Japanese RA patients." (PMID 23437051, 2013). "The genetic background, the presence of high penetrance mutations, environmental factors, and the presence of SAA1 gene haplotype seem to influence the development of amyloidosis too." (PMID 24198817, 2013). "Although the underlying mechanisms for the rapid occurrence of this rare association between TA and amyloidosis remain unclear, carriage of the SAA1.3 allele is likely to be linked to poor outcomes." (PMID 37026007, 2023). "Previous studies have pointed out the value of considering glucocorticoid treatment in cases of inflammatory disease-associated amyloidosis, and our results add weight to this debate by showing that glucocorticoids may increase SAA1 levels in macrophages contributing to amyloidosis in CD." (PMID 29867993, 2018). "A greater understanding of SAA1 and subsequent amyloidosis will open the door to the development of therapeutics to ameliorate amyloid fibrils or slow disease progression." (PMID 37800590, 2023). "SAA1 was highly associated with SARS-CoV-2 (10logp-value = 55), and it has been reported to be involved in the host response to amyloidosis and rheumatoid arthritis." (PMID 33301474, 2020). "For example, alleles in other genes including MHC class-I polypeptide-related sequence A (MICA) and serum amyloid A-1 protein (SAA1) are associated with a severe FMF phenotype and increased susceptibility to amyloidosis." (PMID 31088470, 2019). "Aggregates of SAA1 can be seen in many inflammatory diseases, including CD, resulting in a condition called amyloidosis." (PMID 29867993, 2018). "Of these, a missense variant (rs79681911) of SAA1, initially characterized by serum amyloid a variant (OMIM 104750) and required for the amyloidosis disease process, was identified in our RA patients." (PMID 29340042, 2017). "The risk of amyloidosis depends on contributing factors, such as ethnicity, nature of the MEFV mutation, the SAA1 (serum amyloid A1, OMIM∗104750) gene haplotype, and environmental factors." (PMID 26356190, 2015). "In E. multilocularis-infected C57BL/6 mice, amyloidosis, consisting of a mixture of serum amyloid A1 (SAA1) and (SAA2)-derived AA protein was detected in the kidney, liver and spleen of the experimental animals." (PMID 21283804, 2011). "For example, SAA1/SAA2 are downregulated while SAA3 is upregulated during amyloidosis." (PMID 40420730, 2025). "Amyloidosis research in reptiles and fish has been brief and limited; however, reptiles and fish have low propensity to aggregate systemic amyloidoisis (due to misfolding SAA1)." (PMID 35664543, 2022). "SAA1 is a major acute-phase protein mediating inflammatory amyloidosis." (PMID 36291628, 2022). "Here, we propose HGA as a small molecule disruptor of SAA1, enhancing in vitro amyloid aggregation, thus showing a key role in AKU amyloidosis." (PMID 39273071, 2024). "By contrast, for peripheral amyloidoses, where BBB traversal is not required, such as those caused by transthyretin or serum amyloid A1, a more direct route to testing of therapeutic efficacy of the designs could be available." (PMID 38503834, 2024). "However, being an acute phase reactant, SAA1 is present in the circulation and in exudates during infection or inflammation, even when no amyloidosis occurs." (PMID 29915572, 2018).
AA amyloidosis (24 papers, 2011 to 2025). Secondary amyloidosis is a form of amyloidosis, that complicates chronic inflammatory disorders (mainly rheumatoid arthritis) and is characterized by the aggregation and deposition of amyloid fibrils composed of serum amyloid A protein, an acute phase reactant. "Elevated levels of SAA1 are linked to an increased risk of AA amyloidosis, a condition secondary to chronic inflammation and infection." (PMID 41323809, 2025). "SAA1 is also a precursor to amyloid A (AA), and its accumulation can lead to AA amyloidosis—a condition secondary to chronic inflammation that causes tissue damage and organ dysfunction." (PMID 41323809, 2025). "Recently, a family with AA amyloidosis due to a genetic mutation in the promoter region of the SAA1 gene has also been reported." (PMID 38568326, 2024). "The development of AA amyloidosis has been demonstrated to be positively related to the frequency of SAA1.3 alleles in the Japanese population." (PMID 37026007, 2023). "A cytokine storm during COVID-19 infection will render SAA1 being severely upregulated rendering risk for AA amyloidosis." (PMID 36998202, 2023). "In the present case, the carriage of the SAA1.3 allele likely contributed to the rare association of AA amyloidosis with TA." (PMID 37026007, 2023). "It is clear that genotypes at the SAA1 locus are associated with an increased susceptibility to AA amyloidosis." (PMID 23437051, 2013). "In Japanese patients with RA, homozygote expression of the SAA1.3 allele was a proven risk factor, whereas SAA1.1 appeared to be protective for AA amyloidosis." (PMID 23437051, 2013). "They observed the -13T allele was associated with AA amyloidosis, and associated with the SAA1.3 allele in Japanese RA patients." (PMID 23437051, 2013). "An allelic variant of SAA1.3, was found to be associated with AA amyloidosis in Japanese rheumatoid arthritis (RA) patients." (PMID 23437051, 2013). "One of these genes is SAA1, which encodes for a member of the Serum Amyloid A family, the precursor protein of Amyloid A, and a mutation in the promotor of this gene causes hereditary AA-amyloidosis in humans." (PMID 38136948, 2023). "SAA1.3 risk allele in the SAA1 gene demonstrated in the present case may predispose to AA amyloidosis during the limited periods of TA-related inflammation." (PMID 37026007, 2023). "A mutation in the SAA1 promoter causes a hereditary form of AA-amyloidosis in humans; thus, SAA1 could be of high importance in AA-amyloidosis in cats." (PMID 38136948, 2023). "Furthermore, the SAA1.3/1.3 genotype in Japanese patients with RA was associated with a shorter latency before the onset of AA amyloidosis and more severe AA amyloidosis-related symptoms." (PMID 37026007, 2023). "In Japanese patients, the SAA1.3 allele is a high-risk factor for AA amyloidosis." (PMID 37026007, 2023). "In particular, single nucleotide polymorphisms (SNPs) within the exon 3 of the SAA1 may represent risk factors for the development of AA amyloidosis, as demonstrated for isoform SAA1a (52 Valine/57 Alanine) in Caucasian and SAA1g (52 Alanine/57 Valine) in Japanese population." (PMID 34684086, 2021). "However, we demonstrated that SAA1 gene polymorphisms, which are attributed to AA amyloidosis, might be also responsible for susceptibility to FMF." (PMID 23437051, 2013). "In the onset of AA amyloidosis, the SAA1 is frequently cleaved, producing different forms of SAA1 fragments." (PMID 39273071, 2024). "As a secondary consequence of this chronic inflammation an amyloid fibril seed forms by continuous SAA1 overexpression and proteolytic processing thereof, with can progress to AA amyloidosis." (PMID 36998202, 2023). "The WGS data of SAA1 need to be the focus of future investigations to review if SAA1 is directly involved in hereditary AA-amyloidosis in cats." (PMID 38136948, 2023). "This region also harbors Serum Amyloid A1 (SAA1), an important putative candidate gene for AA-amyloidosis." (PMID 38136948, 2023).